BDNF (brain derived neurotrophic factor)
Diseases named in the same sentence as BDNF in open-access papers (continued):
Sharing a sentence is not in itself a finding about the gene and the disease.
infection (continued). "Our current study only evaluated the acute phase of the disease, and in subsequent studies, the role of endogenous BDNF at different time points during infection process should be investigated." (PMID 32676082, 2020). "We previously demonstrated that theta burst–evoked late-phase long-term potentiation (L-LTP)—a BDNF-dependent form of synaptic plasticity—is impaired in hippocampal area CA1 of aged animals 4 d after infection." (PMID 29911174, 2018). "The forms of long-lasting memory and synaptic plasticity compromised by age and infection are highly dependent on BDNF." (PMID 29911174, 2018). "Previously, we examined the effects of age and infection on memory-related synaptic plasticity and levels of hippocampal BDNF (and related proteins) at a single time point, 4 d after the E. coli injection." (PMID 29911174, 2018). "MAB cells infected with the BDNF-antisense-GFP amplicon vector displayed a strong reduction of pro-BDNF levels beginning as soon as 24 h post infection as compared with uninfected cells or cells infected with the control GFP amplicon vector." (PMID 26954758, 2016). "The decrease of pro-BDNF protein levels was even more prominent at the following time-points, and became essentially complete 96 h after infection." (PMID 26954758, 2016). "As an outcome measure to assess effectiveness of the vectors, we examined levels of the precursor protein for BDNF, i.e. pro-BDNF, for 96 hours after infection using western blot analysis." (PMID 26954758, 2016). "The observed upregulation of BDNF mRNA and protein already at four days after infection suggests that dex is able to delay the increase of BDNF." (PMID 21412436, 2011). "As for BDNF in RSV-induced infection, only a few studies were published." (PMID 39403060, 2024). "In particular, it has shown the significance of BDNF expression and signaling mechanisms in lung development and early airway, crucial in neonatal lung function and also its change in prematurity and insults such as infection and inflammation." (PMID 39403060, 2024). "It was found that a low level of BDNF may disrupt synaptic function and neural plasticity during infection, contributing to long-term cognitive and neurologic impairment." (PMID 35563321, 2022). "At the beginning of infection in immunocompetent hosts, BDNF and NT-3 may reflect endogenous attempts at neuroprotection against Acanthamoeba spp." (PMID 35563321, 2022). "Our attempts to inhibit the consequences of increased release of BDNF either through genetic or pharmacological approaches did not affect acute as well as chronic seizures caused by TMEV infection." (PMID 35874836, 2022). "Our results suggest that at the beginning of infection in immunocompetent hosts, BDNF and NT-3 may reflect an endogenous attempt at neuroprotection against Acanthamoeba spp." (PMID 35563321, 2022). "In conclusion, these results suggest that increased release of BDNF may contribute to TMEV infection-induced seizures by impairing KCC2-mediated maintenance of fast GABAergic inhibition." (PMID 35874836, 2022). "The increment of BDNF levels after the stimulation with HIV-1 gp120 protein could be explained as a protective mechanism against the infection." (PMID 35628626, 2022). "Furthermore, the therapy with CUR significantly increased BDNF levels in the hippocampus at days 21, 28, 60 and 120 post-infection." (PMID 35216083, 2022). "It has been demonstrated that infection with the influenza virus could decrease the levels of BDNF and NGF in the hippocampal region." (PMID 35628626, 2022). "In the present pilot study, we aimed to identify NGF and BDNF changes in the serum of a small cohort of male and female adolescents that contracted the infection during the second wave of the pandemic (between September and October 2020), notably in the absence of available vaccines." (PMID 35626317, 2022).
infection (continued). "Infection with the conditional pathogen Citrobacter, e.g., was shown to induce memory disorders in mice, which went along with decreased expression of brain-derived neurotrophic factor (BDNF)." (PMID 33504065, 2021). "Whether the changes in NGF and BDNF levels in milk from mothers with infection influence their infant’s development remains to be investigated." (PMID 33917718, 2021). "In particular, this system is composed of CaMKII and its regulator NRGN which, in turn, are transcriptionally downregulated in the infection, due to the neurotrophin BDNF, which improves dendrite formation, and re-established at normal expression levels with insulin therapy." (PMID 34946138, 2021). "High BDNF expression level help to protect neurons from infection or stimulation-induced damage." (PMID 34205338, 2021). "Present results revealed that TG infection could increase striatal BDNF level in PD-infected rats in comparison with the PD control rats." (PMID 32461971, 2020). "Moreover, BDNF conditional knockouts exhibited enhanced neutrophil granulocytes infiltration than were observed in their littermate controls at 24 h post-infection." (PMID 32676082, 2020). "The current study indicates that TG infection could improve the cataleptic, asymmetric, nociceptive and behaviors; the level of striatal dopamine release; BDNF levels; TAC; and MDA in PD rats." (PMID 32461971, 2020). "The interaction term (PC NCFxG) revealed to be the most strongly correlated with the neurobehavioral outcomes, indicating the interactions between genotypes (COMT, BDNF) and neonatal factors (infection, invasive procedures, surgery, GA), which were mainly loaded on CA4/DG and alveus." (PMID 30941021, 2019). "We have therefore hypothesized that aging and infection might compromise production or processing of BDNF protein, reducing the availability of BDNF for memory-related plasticity processes at synaptic sites." (PMID 29911174, 2018). "Pretreatment with exogenous BDNF or the tropomyosin-receptor kinase B (TrkB) inhibitor k252a was performed to assess the activation or inhibition of the BDNF/TrkB-signaling axis prior to intracisternal infection with live S. pneumoniae." (PMID 28778220, 2017). "Our findings showed that TrkB expression increased following infection and that administration of exogenous BDNF further elevated TrkB expression, which agreed with our previous findings related to TrkB response to exogenous BDNF in a PM model." (PMID 28778220, 2017). "BDNF expression was significantly higher in the rosiglitazone group on day 9 post-infection." (PMID 24603727, 2014). "Therefore, we cannot exclude that the infection regulates BDNF expression at later time points than the one we tested in the present study." (PMID 25409333, 2014). "(A) AAV-BDNF infection enhances BDNF production in primary cortical neuronal culture." (PMID 24312581, 2013). "BDNF protein production after AAV‐BDNF infection was verified in primary neuronal culture." (PMID 24312581, 2013). "This phenomenon seems to underlie, at least partially, the effect of NPAS4 in increasing the formation of inhibitory synapses, as the number of inhibitory synaptic contacts induced by NPAS4 is moderately attenuated in cells in which BDNF has been knocked down by BDNF-shRNAi infection." (PMID 24024041, 2013). "At five days after infection however, BDNF mRNA and protein levels were increased by dex treatment." (PMID 21412436, 2011). "Two weeks after infection, there was a reduced number of intact neurons in the basal spiral ganglion of infected mice, which were more heterogeneously stained for neurotrophin NT-3 and BDNF than those of healthy control animals." (PMID 21261959, 2011). "Moreover, boosting NGF and BDNF levels may have neuroprotective actions in infections with high neuroinflammatory mechanisms, such as HIV-associated neurocognitive disorders." (PMID 39596862, 2024).
infection (continued). "However, it is still likely that BDNF can signal through the low-affinity receptor p75NTR in microglia, as studies have suggested a subset of microglia express p75NTR, and its expression is upregulated upon infection in mice." (PMID 38254691, 2024). "Moreover, some viruses could steal BDNF/TrkB signaling to endorse neuronal survival, permitting the virus to determine a hidden infection in the nervous system." (PMID 39596862, 2024). "Nevertheless, in mouse and rabbit models of intracerebral or intracisternal infection with S. pneumoniae, an enhancement in neurogenesis has been suggested in the subgranular layer of the dentate gyrus, particularly at earlier time points post infection, as well as increased levels of BDNF." (PMID 37371040, 2023). "Therefore, it can be suggested that the Rab5-positive endosome trafficking due to the infection with HSV-1 could be promoting the BDNF/TrkB signaling." (PMID 35628626, 2022). "Infection with PRV may also affect levels of BDNF in hippocampal neurons." (PMID 36016377, 2022). "In addition, the suppression of BDNF/TrkB signaling by the infection was reversed by administration of the anti-inflammatory cytokine IL-1Ra (interleukin 1-specific receptor antagonist), suggesting a causative role of IL-1β in the infection-evoked reduction in BDNF at the hippocampal synapses." (PMID 35887075, 2022). "The role of BDNF may change over time as the infection evolves." (PMID 32676082, 2020). "Although a growing body of evidence has shown that BDNF participates in regulating intracellular signaling molecules to inhibit the expression of pro-inflammatory cytokines during infection, the exact mechanism by which BNDF exerts its effects in S. pneumoniae infection remains unclear." (PMID 32676082, 2020). "Mice infected with RSV are euthanized at consecutive time points post-infection to collect samples and measure the number of inflammatory cells and levels of interferon-gamma (IFN-γ), nerve growth factor (NGF), and brain-derived neurotrophic factor (BDNF)." (PMID 40050867, 2025). "With respect to the female response to infection-induced neuroinflammation, there was significant upregulation in the expression of CXCL9, CXCL10, BDNF, IL-13 and KCNN4 in the medulla oblongata." (PMID 38879567, 2024). "Here, we confirmed that reactivation in the shuttle box apparatus initiates reconsolidation in the hippocampus, and also illustrated that BDNF is involved in this process, controlling the BRB effect on deficits in memory performance induced by infection." (PMID 37649038, 2023). "We next analyzed the BDNF level in endothelial cells after ANRIL regulation, the results showed that Sh-ANRIL infection reversed BDNF abnormal expression induced by IS stimulation or ANRIL overexpression." (PMID 35906216, 2022). "Both BDNF+/− and WT mice (n = 10 per group; 5 male, 5 female) were infected with TMEV and monitored for behavioral seizures up to 2 weeks post-infection by an experimenter blinded to the genotype of mice." (PMID 35874836, 2022). "In the course of infection, there are also disturbances in neurotransmission and regulation of the HPA axis, as well as a decrease in the level of BDNF—these changes, however, are less consistent with those in BD patients." (PMID 36294388, 2022). "By upregulating the BDNF/TrkB pathway, curcumin improved the viability of PRV-infected hippocampal neurons and provided neuroprotection against infection by PRV." (PMID 36016377, 2022). "To assess the effect of GW2580 on the microglia/macrophage population in BDNF conditional knockout mice, we determined the expression of IBA-1 by immunofluorescence staining at 24 h post-infection." (PMID 32676082, 2020). "When performing pairwise correlation for the ASD cases, BDNF had a significant positive correlation with the other neurodevelopmental factors, VEGF and S100b, and with the inflammatory/infection markers IgA and TARC." (PMID 31591381, 2019).
infection (continued). "BDNF is reduced in neurons with decreased levels of NPAS4 after lentiviral NPAS4-shRNAi infection and primary cell cultures from NPAS4 knockout mice consistently show a similar reduction of depolarization-induced BDNF expression." (PMID 24024041, 2013). "At P15, treatment x sex analysis revealed a significant effect of infection on BDNF expression, but no change to the expression of TGFβ (treatment x sex, BDNF; F = 5.235, p = 0.031, TGFβ; F = 4.009, p = 0.055)." (PMID 38879567, 2024). "In particular, these changes involved mTOR, BDNF, Akt, eEF2, CaMKI, and CREB-dependent signaling cascades in groups treated with monensin or enrofloxacin, and the fewest for doxycycline 15 days after infection." (PMID 39721265, 2024). "By using reverse transcription polymerase chain reaction (RT-PCR), we observed the down-regulation of neurotrophin brain-derived neurotrophic factor (BDNF), glial fibrillary acidic protein (GFAP), and hemagglutinin (HA) in mouse lung during the infection (21 days) of IAV." (PMID 38005876, 2023). "This was associated with the decreased expression in mRNA of BDNF, NGF, and FGF2, and elevated expression of IL-1β in the hippocampus at 6 h post infection, but with no changes in optical intensity of the microglia and astrocytes." (PMID 35741412, 2022). "In the immunosuppressed mice (AS), there was an upward trend in the levels of BDNF in the cerebral cortex and hippocampus in relation to the duration of the infection, but it was not statistically significant." (PMID 35563321, 2022). "Upon infection of NP-derived cells, we were also able, for the first time, to demonstrate a significant upregulation in NGF and BDNF levels over controls, which indicates that, in vivo, C. acnes has the potential to stimulate neurotrophic factors which trigger neo-innervation." (PMID 33652921, 2021). "The authors also observed that BDNF levels were restored during the patient’s recovery, but the elapsed time from the infection to the collection was not reported." (PMID 33917718, 2021). "Moreover, histopathological findings of neurodegeneration and neuronal death were found as infection progressed with activation of p38, JNK and reduction in the BDNF levels." (PMID 33322180, 2020). "The pro- vs. m-BDNF bars should also be separated, as the comparison being highlighted in this figure is pro- vs. m-BDNF, not age or infection as it should be." (PMID 29911174, 2018). "Moreover, animals pretreated with BDNF showed lower bacterial titers as compared with those from the PBS + PM group, and all infected animals lost weight 24 h after infection as compared with the sham group." (PMID 28778220, 2017). "Independently of LiCl treatment, the infection did not significantly alter gene expression of BDNF at 42 hpi." (PMID 25409333, 2014). "However, in the reaction to injury or infection, microglia might overactivate, shifting from their helpful action to focusing on immune defense, which may affect NGF and BDNF availability by promoting neuroinflammation." (PMID 39596862, 2024). "Ca2+-dependent synaptic release of BDNF has been demonstrated in response to spontaneous activity, therefore, it is also likely that the network hyperexcitability ensued following TMEV infection could itself have contributed to the increased levels of BDNF." (PMID 35874836, 2022). "First, we demonstrated that brain-derived neurotrophic factor (BDNF), glial-derived neurotrophic factor (GDNF), neurotrophin-3 (NT3), and their combinations (GBN) could significantly inhibit WSN infection at the NESTIN+ NSCs level, especially BDNF and GBN in NP+ cells." (PMID 35910807, 2022). "In the case of doxorubicin (5 μM), we did not observe any differences between the EV and FV groups, so changes may have only been the effect of infection (C vs. EV: p < 0.05), rather than a combination of Bcl-2 and BDNF overproduction (EV vs. FV: ns)." (PMID 34209365, 2021).
infection (continued). "However, while RSV was able to drastically reduce the levels of nerve growth factor (NGF) after 21 days of infection, the level of brain derived neurotrophic factor (BDNF) was not significantly affected in both the treated and untreated groups." (PMID 26693226, 2015). "Furthermore, increased RNA and protein levels of BDNF were described in a mouse model of PM only 4 days, but not 30 h after infection." (PMID 25409333, 2014). "However, this study was limited by the inability of non-surgical debridement to remove the source of infection completely, which may constrain the full demonstration of the effects of BDNF." (PMID 39589662, 2024). "Lastly, since excessive inflammatory reaction post-TMEV infection is a major driver for the development of seizures in this model (Löscher and Howe, 2022), it is likely that inhibiting BDNF signaling mediated through PLCγ1 alone may not have significant anticonvulsant effects." (PMID 35874836, 2022).